MTOR (mechanistic target of rapamycin kinase)
Diseases named in the same sentence as MTOR in open-access papers (continued):
Sharing a sentence is not in itself a finding about the gene and the disease.
diabetes (continued). "This study investigates the therapeutic mechanisms of Cai’s Herbal Tea in Type 1 Diabetes Mellitus (T1DM) mice, focusing on its effects on mitochondrial change and autophagy via the AMP-activated protein kinase (AMPK)—mammalian target of rapamycin (mTOR) pathway." (PMID 38954041, 2024). "Dapagliflozin effectively prevented the development of HFpEF in rats with diabetes by mitigating nitro-oxidative stress, pro-inflammatory cytokines, myocardial hypertrophy, and fibrosis, reducing apoptosis, and restoring autophagy through AMPK activating and mTOR pathway repressing." (PMID 37386620, 2023). "The diabetes drug canagliflozin inhibits NSCLC cell proliferation and the mammalian target of rapamycin (mTOR) pathway, which mediates cell growth and survival, but it is unclear whether this drug can enhance response rates when combined with cytotoxic therapy." (PMID 37584455, 2023). "In a study based on the Type 2 diabetes mellitus (T2DM) rat diabetic liver injury and neonatal rat cardiomyocyte injury model, a mouse heart failure model, Astragalus polysaccharide and Astragaloside IV were found to restore normal autophagy through the AMPK/mTOR pathway." (PMID 38054830, 2023). "These latter observations are in line with the alteration of the mTOR/AKT/PI3K pathway seen during diabetic retinopathy, the most common complication of diabetes mellitus (DM), a chronic metabolic disease characterized by hyperglycemia." (PMID 37509256, 2023). "It has been shown that autophagy can protect diabetes in a manner independent of mTOR." (PMID 35054822, 2022). "The absence of difference between groups in mTOR protein level could be explained by aberrantly increase in mTOR in diabetes or metabolically stressed conditions." (PMID 36685197, 2022). "Subjects with diabetes showed improvements in insulin sensitivity despite lower meal-induced insulin secretion, increased insulin-sensitizing hormone FGF21, a 1.7-fold increment in mitochondrial activity, lower fasting plasma BCAA levels, and the expression of mTOR." (PMID 34209599, 2021). "Similarly, our previous study found that DJ-1 plays a beneficial role in myocardial I/R in diabetes, and its specific mechanism may be generated by the AMPK/mTOR signaling pathway." (PMID 32347295, 2020). "We also evaluated the expression of SIRT-3 and p-mTOR in non-cancerous adjacent liver tissue of HCC patients with diabetes and/or metabolic syndrome, to verify whether their positive expression was limited to cancerous tissue." (PMID 30917505, 2019). "Notably, key cellular metabolic pathways (mitochondrial dysfunction, EIF2 and MTOR signaling) were also similarly altered in patients with and without diabetes mellitus." (PMID 27495247, 2016). "The protein amount of mTOR was not influenced by maternal diabetes." (PMID 26020623, 2015). "In addition, a significant increase in phospho-Akt/tuberin expression was associated with an increase in Ki67 expression and activation of mTOR in kidney tumor with or without diabetes compared to diabetes alone." (PMID 24797175, 2014). "This may be related to the decreased levels in diabetes of insulin and IGF1, which are both powerful activators of the mTOR pathway and which could act on the insulin-like growth factor receptor which is expressed on small and medium sized dorsal root ganglia neurons." (PMID 18398477, 2008). "Furthermore, the activation of the AKT and mTOR signaling proteins, as well as increased IGF-1 expression, was significantly elevated in the D-T+HIIT group compared to the diabetic control group and other treatment groups, and approached levels observed in the non-diabetes group." (PMID 40362714, 2025). "At both time-points, the kidneys of vehicle-injected diabetic mice had higher ratio of p-mTOR to mTOR, increased abundance of p62, lower abundance of ULK1 and Atg12, and reduced ratio of LC3B to LC3A compared to non-diabetic animals, consistent with diabetes-associated suppression of autophagy." (PMID 38443965, 2024).
diabetes (continued). "However, another research study on rats has suggested that autophagy may be abnormally attenuated in diabetes, where a higher level of PI3K/Akt/mTOR and a low level of Beclin-1 are observed, and inhibiting the PI3K/Akt/mTOR pathway could help with promoting apoptosis and reducing tissue pathology." (PMID 37964954, 2023). "By multivariate analysis, it was found that none of the variables considered (diabetes, BMI, duration of immunosuppressive treatment, duration of renal disease, and concomitant heart disease) showed a statistically significant impact regardless of the presence or absence of mTOR inhibitors." (PMID 35801204, 2022). "Leu treatment resulted in cardiac preconditioning with increased mTOR activity and mitochondrial fusion in both wild-type and HFD-induced obese mice, thereby suggesting that Leu could be potentially used for myocardial I/R injury treatment in patients with diabetes." (PMID 34801078, 2021). "However, Metformin, as a first-line medicine for the treatment of type 2 diabetes mellitus (T2DM), may be a potential drug benefiting diabetic patients with SARS-CoV-2 infection, probably via a suppression of mTOR signaling together with its anti-inflammatory and anti-fibrosis function in lung." (PMID 34690930, 2021). "In the EXIST trials (follow-up up to 5 years), the phase III trials that led to approval of mTOR inhibition in TSC patients, dyslipidemia was reported in 5–30%, but no new cases of diabetes were reported." (PMID 35804402, 2022). "We found no strong evidence that p-ER, EGFR, p-ERK1/2, p-mTOR, or IGF1R are differently expressed in breast tumors of women with and without diabetes." (PMID 29486734, 2018). "Among the top 20 most negatively correlated pathways in the pyruvate metabolic pathway, KEGG Glycosaminoglycan Degradation, KEGG Type II Diabetes Mellitus, KEGG Adherens Junction, KEGG Oocyte Meiosis, Wp Ras Signaling Pathway, KEGG mTOR Signaling Pathway showed a significant negative correlation." (PMID 36685935, 2022). "Therefore, the purpose of the study was to determine the mRNA expression levels of mTOR, Foxp3, IL1β, and IL17A genes in rat parapancreatic adipose tissue with experimental streptozotocin-induced diabetes mellitus, with or without metformin administration." (PMID 32341701, 2020). "Thus, IGF-1, mTOR and IL-15 all are suggested to regulate homeostasis of DETCs, but the coordinate regulation of these pathways of DETC homeostasis in diabetes is not well characterized." (PMID 28729536, 2017).
Insulin resistance (538 papers, 2009 to 2026). Increased resistance towards insulin, that is, diminished effectiveness of insulin in reducing blood glucose levels. "For example, elevated BCAA levels have been linked to activation of mTOR, causing insulin resistance and disruption of neuronal signaling pathways that exert anxiety-like behavior in rats." (PMID 41599935, 2026). "Concurrently, obesity-associated insulin resistance inhibits the mTOR signaling pathway, diminishes muscle anabolic capacity, and drives ectopic lipid deposition within muscle tissue, forming intramuscular lipids (IMCLs)." (PMID 40607039, 2025). "Dysregulation of mTOR signaling is implicated in metabolic disorders, such as obesity and insulin resistance." (PMID 40076782, 2025). "In parallel, hyperactivation of anabolic signaling cascades, particularly the mechanistic target of rapamycin (mTOR) pathway, has been implicated in the development of insulin resistance and has been mechanistically linked to both GDM and ferroptosis." (PMID 41020807, 2025). "It has been observed that gliflozins reduce insulin resistance by decreasing hepatic diacylglycerols, compounds associated with increased insulin resistance, and downregulate cellular signaling through the mammalian target of rapamycin (mTOR) pathway." (PMID 40725186, 2025). "Overactivation of mTOR can cause insulin resistance in humans and has been implicated in type 2 diabetes." (PMID 39859520, 2025). "Chronic BCAA-driven mTOR overactivation has been linked to insulin resistance (IR), a metabolic condition increasingly associated with AD and PD." (PMID 40725241, 2025). "Metabolic syndrome: Dysfunction in mTOR signaling is strongly linked to the symptoms of type 2 diabetes, including whole-body insulin resistance, hyperglycemia, and hyperlipidemia." (PMID 41356921, 2025). "Enhanced mTOR activity is also linked to insulin resistance, while calorie restriction and short-term rapamycin treatment enhanced insulin sensitivity and glucose uptake." (PMID 39177917, 2024). "The phosphorylation of the mammalian target of rapamycin (mToR at Ser2448) was also linked with the condition of insulin resistance." (PMID 39795155, 2024). "mTOR is a prognostic marker of diabetic microvascular and is associated with insulin resistance in patients with T2DM." (PMID 39261960, 2024). "Conversely, elevated levels of BCAAs have been associated with insulin resistance, potentially due to their influence on mTOR signaling and the promotion of inflammatory pathways." (PMID 39211341, 2024). "Yet, mTOR inhibition leads to reduced β-cell function, insulin resistance, and limited insulin secretion associated with the progression of DM." (PMID 37238686, 2023). "mTOR activation in patients with metabolic syndrome has also been found to be diminished and possibly responsible for insulin resistance with an increased risk of vascular thrombosis." (PMID 37238686, 2023). "The insulin receptor substrate 1 (IRS-1) is another key target of mTOR signaling that is associated with insulin resistance and an important regulator of insulin-stimulated glucose metabolism." (PMID 37830621, 2023). "By participating in several different signaling pathways in the human body, the mammalian Target of Rapamycin (mTOR) controls cell division, autophagy, and apoptosis, being linked to insulin resistance, osteoporosis, cancer, and rheumatoid arthritis." (PMID 37176098, 2023). "Reduced activation of the AKT-mammalian target of rapamycin (mTOR)-phosphoprotein 70 ribosomal protein S6 kinase (p70S6K) signaling pathway in skeletal muscle, caused by insulin resistance (IR) and insulin deficiency, leads to decreased protein synthesis." (PMID 37438792, 2023). "Mechanistically, insulin resistance is associated with increased serine phosphorylation of the insulin receptor substrate (IRS) mediated by serine/threonine kinases including mTOR and p70S6K." (PMID 36982168, 2023).
Insulin resistance (continued). "Brain insulin resistance is associated with hyperactivation of the mechanistic target of rapamycin (mTOR)." (PMID 35707855, 2022). "Chronic overnutrition increases mTOR signaling, which is associated with the development of insulin resistance (IR)." (PMID 35761356, 2022). "Some studies have demonstrated that the benefit of aerobic exercise on insulin resistance is associated with the suppression of mTOR/S6K signaling pathway in skeletal muscle." (PMID 36358588, 2022). "In agreement with this evidence obtained in studies investigating protein metabolism, the metabolic state of obesity is often linked to prolonged activation of mTOR, a condition that induces tissue insulin resistance." (PMID 35350688, 2022). "The association of p62 with AKT and GLUT4, or mTOR, and the detailed molecular mechanisms whereby p62 induces an increase in skeletal muscle mass and an amelioration of insulin resistance require further study." (PMID 36439272, 2022). "Genetic disruption of the mTOR pathway in skeletal muscle causes insulin resistance in mice, but disruption in adipose increases insulin sensitivity." (PMID 36095197, 2022). "Inhibition of the mTOR pathway using rapamycin prevented insulin resistance caused by chronic hyperinsulinemia in liver and muscle." (PMID 33868799, 2021). "mTOR has been reported to play a pathogenic role in insulin resistance and adipogenesis in several cell types." (PMID 34177809, 2021). "Mechanistically, EA ameliorated autophagy deficiency-mediated insulin resistance via inactivation of mTOR/4E-BP1 signaling pathway." (PMID 32698821, 2020). "The mTOR/receptor complex is activated by Akt and phosphorylase S6 Kinase, which has been reported to cause insulin resistance by serine phosphorylation of insulin receptor substrate-1 (IRS-1), eventually disrupting PI3K-Akt signaling." (PMID 32294959, 2020). "Recent studies have indicated that the abnormal expression of the PI3K/Akt/mTOR signal pathway can impair various ovarian functions, induce the risk of insulin resistance, and affect the proliferation of follicles." (PMID 33029296, 2020). "Scientists have also linked mTOR to various disease processes, such as tumor formation, arthritis, insulin resistance and osteoporosis." (PMID 32175074, 2020). "Insulin resistance is highly associated with the overexpression of PI3K/Akt/mTOR signal pathway, which is a universal kinase that has been appeared in the control of different growth factors and hormones." (PMID 33029296, 2020). "Mechanically, EA attenuated autophagy deficiency-mediated insulin resistance in PCOS-like rats via inactivating mTOR/4E-BP1 signaling pathway." (PMID 32698821, 2020). "Studies have shown that the mTOR signaling pathway is also associated with cancer, arthritis, insulin resistance, osteoporosis, and other diseases." (PMID 32175074, 2020). "For example, overactivation of mTOR can cause insulin resistance in humans and has been implicated in type 2 diabetes." (PMID 31406105, 2019). "Prolonged activation of the mTOR signaling pathway in liver and skeletal muscle of obese rats suggested a possible role of mTOR in obesity-linked insulin resistance." (PMID 30609721, 2019). "It is obvious that mTOR has multiple roles in metabolism and, when overactivated by nutrient overload and obesity, participates in causing glucose intolerance and insulin resistance." (PMID 30034573, 2018). "Hyperglycemia and hyperlipidemia were linked to the mTOR inhibitors, but Lamming et al43 reported that mTORi provided longevity beyond the insulin resistance." (PMID 30117312, 2018). "There is evidence for a pathogenetic link between increased BCAAs plasma levels, persistent activation of mTOR, ribosomal protein S6 kinase 1 and higher risk of developing insulin resistance and T2DM." (PMID 30532260, 2018).
Insulin resistance (continued). "As we have already mentioned, it is important to emphasize that both nutrients and insulin activate mTOR, but the overactivated mTOR further causes insulin resistance by at least two mechanisms." (PMID 30034573, 2018). "This increased degradation of IRS1, caused by hyperphosphorylation on serine/threonine residues, can lead to insulin resistance associated with the mTOR overactivation." (PMID 30034573, 2018). "Deregulation of PI3k/Akt mediated mTOR signaling pathway contributes to insulin resistance and associated conditions." (PMID 28659828, 2017). "Deregulation of entities in mTOR associated BRN result in certain other complications like insulin resistance and type 2 diabetes." (PMID 28659828, 2017). "A dysregulation of the mTOR pathway has in turn been implicated in several pathological conditions including insulin resistance and cancer." (PMID 27826244, 2016). "These underlined the attractiveness of mTOR as a therapeutic target to overcome both insulin resistance and cancer." (PMID 27826244, 2016). "Excessive activation of the Akt/mTOR pathway has a crucial role in obesity-associated insulin resistance, and is critically important in liver carcinogenesis." (PMID 25879666, 2015). "Activation of the Akt/mTOR pathway has a crucial role in obesity-associated insulin resistance, and is critically important in liver carcinogenesis." (PMID 25879666, 2015). "In contrast to the oncogenic hyper-activation of the PI3K/Akt/mTOR pathway, it is the hypo-activation of this pathway that attenuates cellular insulin response, causing insulin resistance and even T2D." (PMID 25334061, 2014). "Chronic administration of the mTOR inhibitor rapamycin has been shown to substantially impair glucose tolerance and insulin action, inducing muscle insulin resistance despite weight loss in rats." (PMID 23822543, 2013). "In mice, sustained activation (by high fat feeding) of mTOR is associated with hepatic insulin resistance." (PMID 22683661, 2012). "In healthy men, rapamycin prevented activation of mTOR and insulin resistance caused by amino acid mixture." (PMID 22683661, 2012). "For example in the liver and fat, hyper-active mTOR causes insulin-resistance, which in turn leads to activation mTOR in beta-cells, which produce insulin." (PMID 22246147, 2011). "It has been asserted that higher concentrations of BCAA in obesity cause or exacerbate insulin resistance through mechanisms involving activation of the molecular target of rapamycin (mTOR)." (PMID 21170321, 2010). "Despite these advances, the use of first- and second-generation mTOR inhibitors has been associated with a range of side effects such as insulin resistance, hyperglycemia, impaired wound healing, hypertension, and various metabolic, renal, and pulmonary complications." (PMID 41469379, 2025). "Dysregulation of the mTOR pathway is implicated in insulin resistance." (PMID 41007744, 2025). "Thus, hyperactivation of mTOR in many tissues during obesity causes defective glucose metabolism, increased fat storage, and insulin resistance and is, thus, an important target for the therapy of obesity-associated metabolic disorders." (PMID 40218884, 2025). "Hypothetically, in GD placentas, the decrease in mTOR caused by insulin resistance may lead to dephosphorylation of TFEB and its translocation to the nucleus." (PMID 41226334, 2025). "The chronic inhibition of mTOR is shown to be associated with insulin resistance and glucose intolerance and may also lead to type 2 diabetes." (PMID 39177917, 2024). "However, long-term use of other mTOR inhibitors, such as rapamycin, are known to cause insulin resistance and β-cell toxicity." (PMID 39386475, 2024). "Other studies speculate the reason could be that high concentration of BCAAs causes insulin resistance by activating the mammalian target of rapamycin (mTOR) signaling." (PMID 36837846, 2023). "mTOR signaling pathways are associated with cancer, insulin resistance, and other disorders." (PMID 37597078, 2023).